OAS1 (2'-5'-oligoadenylate synthetase 1)
Diseases named in the same sentence as OAS1 in open-access papers (continued):
Sharing a sentence is not in itself a finding about the gene and the disease.
age-related macular degeneration (1 paper, 2019). Age-related loss of vision in the central portion of the retina (macula), secondary to retinal degeneration. "In another study, treatment of retinal pigment epithelium (RPE) cells with amyloid-β1-40, a known inflammatory trigger in Age-related macular degeneration (AMD) caused a significant induction of inflammatory genes such as BST2, STAT1, RSAD2, MX2, OAS1&2, IFNL44 and LXN43." (PMID 30914656, 2019).
amyloid (1 paper, 2025). "Therefore, we propose that carriers of the minor alleles of OAS1 will demonstrate a quicker response to amyloid deposition, the clearance of dsRNA, the lowering of inflammation, and reduced cell death." (PMID 39859237, 2025).
anemia (1 paper, 2012). A reduction in the number of red blood cells, the amount of hemoglobin, and/or the volume of packed red blood cells. "Anemia was associated with the OAS1 rs2660 and the CTL4 rs231775 polymorphisms, and neutropenia and thrombocytopenia were associated with the polymorphism rs4969170 in the SOCS3 gene." (PMID 23133602, 2012). "Anemia was associated with OAS1 and CTLA4 gene polymorphisms (p = 0.049 and p = 0.045, respectively), neutropenia and thromobocytopenia were associated with SOCS3 gene polymorphism (p = 0.02 and p = 0.002, respectively)." (PMID 23133602, 2012).
atherosclerosis (1 paper, 2025). A disease characterized by the build-up of fatty material and calcium deposition in the arterial wall resulting in partial or complete occlusion of the arterial lumen. "Using a Venn diagram to identify the shared genes, we identified six candidate downstream molecules potentially regulated by AP‐1 and involved in vascular endothelial dysfunction and atherosclerosis induced by OSS: NR4A1, ZNF467, LGAL59, OAS1, OAS2, and TGM2." (PMID 40492401, 2025).
breast tumors (1 paper, 2024). "Taken together, these findings underscore the distinct expression patterns of OAS1, OAS2, OAS3, and OASL in breast tumors across a spectrum of immune and molecular subtypes." (PMID 39633486, 2024).
chronic hepatitis C virus infection (1 paper, 2017). Chronic form of hepatitis C infection. "The A allele of rs10774671 is correlated with reduced OAS1 enzymatic activity in human peripheral blood mononuclear cells, and is associated with increased susceptibility to West Nile virus and chronic hepatitis C virus infections." (PMID 28640813, 2017).
chronic kidney disease (1 paper, 2022). Impairment of the renal function secondary to chronic kidney damage persisting for three or more months. "Opposite, other studies showed that OAS1 might play a critical role in regulating the development of chronic kidney disease (CKD)." (PMID 36553678, 2022).
cognitive decline (1 paper, 2022). "In humans, prolonged upregulation of the OAS1 gene family has been reported to induce chronic inflammatory conditions that may cause cognitive decline, so further studies on this gene may be beneficial in predicting inflammation-related AD risk." (PMID 35958988, 2022).
colon cancer (1 paper, 2024). "We selected eight representative immune-related molecules for qPCR validation in SW480 and another colon cancer cell line HT29: DDX58, CHST4, TNFSF18, XAF1, OAS1, IFI27, IFI44, IFIT3." (PMID 38281029, 2024). "DDX58, XAF1, OAS1, IFI27, IFI44 or IFIT3 was indeed downregulated and CHST4 or TNFSF18 was upregulated in MDM4 overexpressed colon cancer cells." (PMID 38281029, 2024).
dementia (1 paper, 2025). Loss of intellectual abilities interfering with an individual's social and occupational functions. "The genotyping of five SNPs across the OAS1 locus was conducted in the Brains for Dementia Research (BDR) Cohort for association with AD." (PMID 39859237, 2025). "The genotyping of OAS1 SNPs was undertaken in the Brains for Dementia Research (BDR) project cohort, accompanied by the exploration of RNA-sequencing data quantifying gene expression and splice variants of OAS1 in several samples from this cohort." (PMID 39859237, 2025). "The data presented here suggest further exploration of the OAS1 gene in relation to dementia is warranted." (PMID 39859237, 2025). "Therefore, despite the observation of increases in OAS1 expression in dementia-relevant models, it may not be active." (PMID 39859237, 2025).
depression (1 paper, 2023). "Previous genome-wide association studies have identified associations between OAS1 and neuroticism, risk taking, depression, and Parkinson’s disease." (PMID 37398583, 2023).
dermatomyositis (1 paper, 2021). Dermatomyositis (DM) is a type of idiopathic inflammatory myopathy characterized by evocative skin lesions and symmetrical proximal muscle weakness. "In conclusion, a total of 3 genes associated with the development of dermatomyositis—MX2, OAS1, and OAS2—were identified in this study through a series of information biology analyses, which are expected to be biomarkers or drug targets to some extent for the diagnosis of dermatomyositis." (PMID 35003257, 2021). "The results showed that MX2, OAS1, and OAS2 were significantly upregulated in the GSE11971 and GSE142807 datasets compared to normal samples in dermatomyositis samples." (PMID 35003257, 2021).
enterovirus infection (1 paper, 2021). "Type I-IFN plays a critical role in the innate immune response as the first line of defense against enterovirus infection and regulates many immune responsive genes, including IFN-β, IFI-27, ISG15, and OAS-1." (PMID 34485180, 2021).
HCMV infection (1 paper, 2021). "Inhibition of CXCL10, MX1, and OAS1 by UL23 at late times after HCMV infection was observed in this study, so UL23 protects HCMV against the immunomodulatory and antiviral responses of IFN-I." (PMID 34305856, 2021).
herpes simplex infection (1 paper, 2022). "After treatment of a metastatic BC patient with herpes simplex infection pathway (associated KGs: OAS1, OAS3, ATF6B, IRF9), there has created a case of Sweet Syndrome." (PMID 35617355, 2022).
Hyperglycemia (1 paper, 2024). An increased concentration of glucose in the blood. "However, in one study, the OAS1 gene rs11066453 variant (p=4.53×10-9) was associated with 1-hour oral glucose tolerance test (OGTT) hyperglycemia (1-hPG), but not fasting plasma glucose or 2-hP." (PMID 38694517, 2024).
immunodeficiency disease (1 paper, 2023). Disease in which there is a deficiency or defect in the mechanisms of immunity, either cellular or humoral. "A recent report showed that OAS1 gain-of-function variants cause exogenous RNA-independent immunodeficiency disease through RNase L-mediated RNA cleavage leading to transcriptomic alterations, translational arrest, dysfunction and apoptosis of monocytes, macrophages, and B-cells." (PMID 37564647, 2023).
infiltrating bladder urothelial carcinoma (1 paper, 2022). An invasive transitional cell carcinoma that arises from the urinary bladder urothelium. "OAS1 was overexpressed with a fold change of 8.816 in superficial bladder cancer, and with a fold change of 2.755 in infiltrating bladder urothelial carcinoma, in the Sanchez-Carbayo bladder 2 dataset." (PMID 36162993, 2022).
intestine cancer (1 paper, 2023). "We initially investigated the expression of OAS1 in the CCLE database and observed high expression levels in organs of the digestive system such as the pancreas and intestine cancer cells." (PMID 37928544, 2023).
kidney injury (1 paper, 2023). Trauma to the kidney. "Expression of ISGs (Mx1, Isg15, Isg20, Ifitm1, Bst2, and Oas1), and immune cell markers Lyz2 and Cd68 were markedly lower in 3TC mice with FA-induced kidney injury compared to controls." (PMID 36732547, 2023).
leprosy (1 paper, 2018). Leprosy is a chronic infectious disease affecting primarily the skin and peripheral nervous system. "Linear regression analysis indicates that CD163 and OAS1 expression are coordinately expressed (P = 0.0004, R2 = 0.6019) and two way ANOVA analysis confirms that leprosy type of the lesion is significantly (P = 0.0003) associated with differential gene expression of CYP27B1, CD163 and OAS1." (PMID 30300363, 2018). "Consistent with these in vitro studies, an inverse relationship between expression of CYP27B1 vs. type I IFN downstream gene OAS1 was detected in leprosy patient lesions, leading us to study cytokine-derived macrophages (MΦ) to model cellular responses at the site of disease." (PMID 30300363, 2018).
lupus nephritis (1 paper, 2023). Glomerulonephritis in the context of systemic lupus erythematosus. "Moreover, OAS1, OAS2, and OAS3 were closely related to lupus nephritis (LN) progression." (PMID 36655136, 2023).
lymph-node metastasis (1 paper, 2020). "In addition, significant correlations were observed between OAS1 expression and lymph-node metastasis (p = 0.001) and TNM stage (p = 0.048)." (PMID 32850406, 2020). "MS4A1 was expressed higher in women and the older (>65 years), stage N0, stage T1&T2, and stage I&II patients, while in the patients with lymph-node metastasis and advanced TNM stage, OAS1 had higher expression." (PMID 32850406, 2020).
myelofibrosis (1 paper, 2022). A partial or complete replacement of the bone marrow stroma by fibrous tissue. "Additionally, the four genes (OAS1, IFITM3, GBP1, and GBP2) we identified in this study might have the potential to be auxiliary diagnostic and predictive indicators of myelofibrosis, but further investigations are still necessary in the future." (PMID 36061178, 2022). "Therefore, these four genes (OAS1, IFITM3, GBP1, and GBP2), especially OAS1, might possess the potential to be novel auxiliary diagnostic and predictive indicators of myelofibrosis, but further research is still necessary in the future." (PMID 36061178, 2022). "The results showed high AUC values of the four genes (OAS1, IFITM3, GBP1, and GBP2) when distinguishing JAK2V617F+ myelofibrosis from JAK2V617F+ PV or ET." (PMID 36061178, 2022). "The external datasets validated the upregulation of four interferon-related genes (OAS1, IFITM3, GBP1, and GBP2) in JAK2V617F+ myelofibrosis." (PMID 36061178, 2022). "Furthermore, we identified four potentially important genes (OAS1, IFITM3, GBP1, and GBP2) that were upregulated uniquely in myelofibrosis." (PMID 36061178, 2022). "Overall, the four interferon-stimulated genes (OAS1, IFITM3, GBP1, and GBP2) exclusively upregulated in myelofibrosis might not only provide important novel clues to the MPN field but also offer special insights into the effects of IFN signaling on the pathogenesis of myelofibrosis." (PMID 36061178, 2022).
neuroblastoma (1 paper, 2023). Neuroblastoma (NB) is the most common solid, extracranial childhood tumor. "Here, we describe the protein expression levels of OAS1, OAS2, OAS3, and OASL in cells forming the NVU, such as primary human brain pericytes, astrocytes, EC, immortalized human microglial cells, and SH-SY5Y neuroblastoma cell line." (PMID 37209263, 2023).
osteosarcoma (1 paper, 2020). A usually aggressive malignant bone-forming mesenchymal neoplasm, predominantly affecting adolescents and young adults. "The results demonstrated that gene changes of CXCL10 (P = 0.044), GNAI1 (P = 0.048), MYC (P = 0.011), and OAS1 (P = 0.0091) were significantly correlated with the overall survival of osteosarcoma patients." (PMID 32974202, 2020).
pancreatic ductal adenocarcinoma (1 paper, 2022). An infiltrating adenocarcinoma that arises from the epithelial cells of the pancreas. "In Badea Pancreas dataset, OAS1 was highly expressed in pancreatic ductal adenocarcinoma with a fold change of 2.583 compared with normal pancreatic tissues." (PMID 35719943, 2022).
primary immunodeficiencies (1 paper, 2025). "This is supported by the fact that among the 38 interferon response genes (category II), only OAS1, ADAR, PSMB8, SAMHD1 and the IRF transcription factors have been implicated in causing primary immunodeficiencies." (PMID 41038828, 2025).
prostate adenocarcinoma (1 paper, 2023). "In addition, high OAS1 expression was associated with poor DFS (disease-free survival), including LGG (P=0.0049), LUAD (P=0.019), PRAD (Prostate adenocarcinoma) (P=0.027), and UVM (P=0.0087)." (PMID 37746262, 2023).
prostate tumors (1 paper, 2013). "This analysis revealed a prominent inverse correlation between uc.106 + A expression and the expression of many interferon pathway genes such as IRF7, ISG15, ISG20, OAS1-3, and PTPN22 in prostate tumors." (PMID 23409773, 2013).
relapsing remitting MS (1 paper, 2018). "The expression of intracellular IL-33 and IL-33-regulated genes such as OAS1, GATA3, and PMAIP1 was increased in relapsing remitting MS patients (RRMS)." (PMID 29507527, 2018).
reovirus infection (1 paper, 2017). "Not surprisingly, reovirus infection stimulated a strong increase in genes associated with an anti-viral response in both cell lines, including OAS1, OAS2, and OAS3." (PMID 29156834, 2017).
scrub typhus (1 paper, 2022). Scrub typhus is a rare dust mite-borne infectious disease caused by the Orientia tsutsugamushi bacterium and characterized clinically by an eruptive fever which is potentially serious. "Additionally, dual-RNA sequencing has uncovered a high degree of Mx1 and Oas1 gene expression in O. tsutsugamushi-infected human umbilical vein endothelial cells and a genome-wide association study of scrub typhus patients recently implicated Oas1 in susceptibility to disease." (PMID 36678402, 2022).
steatosis (1 paper, 2024). Increased lipid within the cytoplasm of cells. "In GSE89632 dataset with the highest number of participants, OAS1 expression is significantly upregulated also in steatosis versus healthy." (PMID 39562169, 2024).
thrombosis (1 paper, 2024). "However, the presence and extent of recurrence of thrombosis were positively associated with the expression of IFI44, OAS1, and RSAD2 as well as with the IFN score in patients with SAPS." (PMID 38550580, 2024).
tick-borne encephalitis (1 paper, 2023). Tick-borne encephalitis is caused by an arbovirus of the Flaviviridae family (tick-borne encephalitis virus, TBEV), transmitted principally by the bite of the Ixodes ricinus tick. "rs10774671 (OAS-1; G > A) has been involved in TB, HBV, HCV, tick-borne encephalitis (TBE), WNV, and severity of hand, foot, and mouth disease, and more recently, SARS-CoV-2." (PMID 36833454, 2023).
uveal melanoma (1 paper, 2023). A melanoma derived from melanocytes of the uveal tract. "Patients with high expression of OAS1 showed poor OS (overall survival), including ACC (Adrenocortical carcinoma) (P=0.0077), LGG (Brain lower grade glioma) (P=0.025), LIHC (P=0.025), LUAD (P=0.0081), PAAD (P=0.047), and UVM (Uveal Melanoma) (P=0.0035)." (PMID 37746262, 2023).
wart (1 paper, 2021). "In immunohistochemical staining, the expressions of ISGs such as ISG15, OAS1, and MxA commonly declined in HPV-2 wart samples." (PMID 33670861, 2021).
infection (166 papers, 2008 to 2026). The state of being infected such as from the introduction of a foreign agent such as serum, vaccine, antigenic substance or organism. "Our study with a relatively small cohort successfully identified OAS1 (rs1311454) as a risk factor for severe infection, consistent with the results of a large GWAS." (PMID 37564647, 2023). "OAS2 and OAS3 recognize dsRNA in different ways, which provides an additional means of activating RNase L, potentially reducing OAS1 activity loss during infection." (PMID 36670749, 2023). "Alternative splicing of OAS1 results in several isoforms with different enzymatic activity, and the splice site polymorphism rs10774671 has been associated with infection by viruses." (PMID 32787775, 2020). "Together, these data suggest that OAS1 activity modulates early viral replication, and that decreased OAS1 activity is associated with increased risk of infection and seroconversion." (PMID 19247438, 2009). "Together, these data identify OAS1 SNP rs10774671 as a host genetic risk factor for initial infection with WNV in humans." (PMID 19247438, 2009). "Here we show that a specific human mutation that results in reduced function in a known antiviral gene named OAS1 is associated with increased rate of infection with West Nile virus, a member of the flavivirus family." (PMID 19247438, 2009). "Instead, we found a consistent association of an OAS1 SNP and infection with WNV from samples collected from five independent US centers, and with WNV replication in human lymphoid tissue ex vivo." (PMID 19247438, 2009). "Interestingly, a recent pre-print demonstrated a link between inter-individual differences in the expression of anti-SARS-CoV-2 alleles of OAS1 in determining IFN-mediated cellular resistance to infection and subsequent disease." (PMID 35436306, 2022). "OAS1 genetic variants were linked to infection and excessive morbidity in the SARS-CoV outbreak." (PMID 35421191, 2022). "The present study provides the first evidence in support of the hypothesis that OAS1 influences risk of infection in response to WNV exposure in humans." (PMID 19247438, 2009). "We validate numerous targets cleaved during infection, including the giant sarcomeric protein obscurin and the innate immune protein OAS1." (PMID 41729072, 2026). "Total RNA was extracted 4 and 8 h post-infection, after which the relative levels of IFNβ, OAS1, MX1, and MX2 RNAs were determined by quantitative real-time PCR (qRT-PCR)." (PMID 41585476, 2026). "This reduction infection was associated with decreased mRNA expression of TLR3 and TLR7, along with increased expression of antiviral genes, including PKR and OAS1." (PMID 40839599, 2025). "Knockdown of DCAF7 had a relatively minimal effect on suppression of IFI6, IFIT1, OAS1&2 while affecting IFIT2 slightly more with HAdV-B7 infection." (PMID 38940561, 2024). "Similar results were observed at the transcript level on day two post-infection for antiviral genes Ifit3, Mx1, and Oas1, with SEOV inducing minimal gene expression." (PMID 39585900, 2024). "Infection with 60 ng/ml of HIV-1 for 24 or 48 h resulted in a significant increase in the expression of OAS1, OAS2, OAS3, and OASL at the mRNA level." (PMID 37209263, 2023). "Here, we found an induced antiviral effect of the poly I:C pre-treatment (12 h before RV-A1b infection) on OAS-1, IFN-λ, and IFN-β expression." (PMID 38140569, 2023). "The expression of OAS1 protein was increased only 24 h after infection and returned to control levels after a longer infection period." (PMID 37209263, 2023). "Moreover, a membrane-associated OAS1 form could act as a ds-RNA sensor in infection sites." (PMID 36298734, 2022). "Upregulation of many genes associated with activation of innate immunity and SARS CoV-2 disease severity were identified during acute (4 dpi) SARS-CoV-2 (Delta variant) infection in cats, such as KIF11, IRF7, OAS1, BATF2, IF16, and BPIFA1." (PMID 35746678, 2022).